RNA5S1 (RNA, 5S ribosomal 1)
Synonyms: RN5S1
Gene: Ribosomal RNA gene on chromosome 1 (228,610,268 to 228,610,386, reverse strand). Ensembl gene ENSG00000199352.
Gene Ontology:
Molecular function: structural constituent of ribosome
Cellular component: ribosome
Homologues: Paralogues in human: RNA5S10 (100% identical), RNA5S11 (100% identical), RNA5S12 (100% identical), RNA5S13 (100% identical), RNA5S14 (100% identical), RNA5S15 (100% identical), RNA5S16 (100% identical), RNA5S17 (100% identical), RNA5S2 (100% identical), RNA5S3 (100% identical), RNA5S4 (100% identical), RNA5S5 (100% identical), and 26 more.